INPP4B (inositol polyphosphate-4-phosphatase type II B)
Diseases named in the same sentence as INPP4B in open-access papers (continued):
Sharing a sentence is not in itself a finding about the gene and the disease.
prostate tumors (4 papers, 2014 to 2023). "Thus, INPP4B plays a crucial role in maintenance of overall metabolic health and protects from prostate neoplasms associated with metabolic dysfunction." (PMID 33772116, 2021). "Taken together, we discovered that INPP4B is a novel suppressor of oncogenic PKC signaling, further emphasizing the role of INPP4B in maintaining normal physiology of the prostate epithelium and suppressing metastatic potential of prostate tumors." (PMID 25248616, 2014). "Importantly, prostatic neoplasms were detected only in HFD Inpp4b−/− males, suggesting a modulatory role for INPP4B in obesity-induced prostatic neoplasms." (PMID 33772116, 2021). "Contrary to PTEN, there was a positive correlation between INPP4B and EZH2 expression in normal human prostates and early-stage prostate tumors." (PMID 38001678, 2023). "Consistent with a hypothesis of compensatory downregulation of EZH2 in early prostate tumorigenesis, the positive correlation between INPP4B and EZH2 is only evident in the primary prostate tumors." (PMID 38001678, 2023). "In the absence of clinical samples obtained before and soon after castration, it was not possible to demonstrate androgen regulation of INPP4B in human prostate tumors." (PMID 25248616, 2014).
bladder cancer (3 papers, 2015 to 2023). "It has been reported that increased ER-α in BC cells suppresses bladder cancer cell growth by downregulating INPP4B which, in turn, suppresses the AKT signaling pathway." (PMID 37900178, 2023). "In bladder cancer cells, estrogens were shown to upregulate INPP4B via the ERα pathway, resulting in inhibition of AKT activity and cell growth." (PMID 26770009, 2015). "INPP4B has been recognized as a tumor suppressor of several types of malignancies, such as breast and prostate cancers, but its role in bladder cancer remained unclear." (PMID 26770009, 2015). "Chromatin immunoprecipitation assay further revealed that ERα could bind to a putative estrogen response element region of the INPP4B promoter in bladder cancer cells." (PMID 26770009, 2015). "Thus, our findings confirm the known tumor-suppressive role of INPP4B in bladder cancer, and uncover three new contexts where INPP4B expression status may be prognostically significant." (PMID 29415082, 2018).
glioma (3 papers, 2022 to 2025). A benign or malignant brain and spinal cord tumor that arises from glial cells (astrocytes, oligodendrocytes, ependymal cells). "Thus, we presume that INPP4B loss results in glioma’s immune resistance, in which PD-L1 plays a key role, in a similar way as during PTEN loss." (PMID 36147923, 2022). "INPP4B expression was significantly reduced in gliomas, and overexpression of INPP4B suppressed glioma expression." (PMID 37088950, 2023). "INPP4B expression is significantly reduced in gliomas, and overexpression of INPP4B inhibits glioma cell proliferation, migration, apoptosis resistance, PD‐L1 expression, and T‐cell suppression." (PMID 37088950, 2023). "Mechanistic findings suggest that INPP4B inhibits immune escape from glioma by downregulating PI3K/AKT signaling and thereby suppressing PD‐L1 expression." (PMID 37088950, 2023). "Overexpression of INPP4B inhibited glioma cell proliferation, migration, apoptosis resistance, PD‐L1 expression, and T cell suppression." (PMID 37088950, 2023). "Mechanistic findings showed that INPP4B inhibited PD‐L1 expression and thus glioma immune escape through downregulation of PI3K/AKT signaling." (PMID 37088950, 2023). "Through the combined analysis of glioma patients’ samples, glioma cell lines and our mouse glioma model, we found that INPP4B is indeed under-expressed in gliomas, while it is highly expressed in normal astrocytes." (PMID 36147923, 2022). "Recent studies found low INPP4B expression in gastric cancer, breast cancer and other tumor tissues, but there are few data on glioma." (PMID 36147923, 2022). "To further demonstrate the beneficial role of INPP4B on restricting glioma growth, we sought to inhibit INPP4B expression in U87 and U251 cells." (PMID 36147923, 2022). "In contrast to INPP4B overexpression, INPP4B knockdown resulted in increased proliferation, migration of glioma cells, and reduced G0/G1 cell cycle arrest." (PMID 36147923, 2022). "Here, we confirmed that INPP4B expression is markedly diminished in glioma compared with healthy brain tissues." (PMID 36147923, 2022). "Further, INPP4B mRNA and protein levels were significantly lower in the murin glioma cell line GL261 than in primary astrocytes." (PMID 36147923, 2022). "Altogether, these observations suggest that INPP4B negatively regulates PI3K/AKT signaling in glioma." (PMID 36147923, 2022). "Here, we confirmed that INPP4B expression is often downregulated in low- and high-grade human glioma tissues, in tissues from an orthotopic mouse model of brain glioma and in glioma cells." (PMID 36147923, 2022). "Altogether, these data suggest that impaired INPP4B expressionmay play an important role in glioma progression." (PMID 36147923, 2022). "To test a potential link between INPP4B downregulation and glioma progression, we constructed an INPP4B-overexpressing vector (pcDNA3.1-INPP4B), using a scramble-overexpressing vector (pcDNA3.1-Scramble) as negative control." (PMID 36147923, 2022). "INPP4B mRNA and protein levels were significantly lower in glioma cell lines (U251, U87, U373) than in the astrocyte cell line HA1800." (PMID 36147923, 2022). "Further, INPP4B negatively regulates the expression of PD-L1, which likely compromises the ability of the glioma cells to escape immune surveillance and cytotoxicity." (PMID 36147923, 2022). "The level of INPP4B expression was evidently higher in normal brain tissues than in low- and high-grade glioma tissues." (PMID 36147923, 2022). "To further explore the potential mechanism whereby INPP4B inhibits glioma cell growth, we quantified phosphorylated PI3K and AKT, which represent two key factors in this signaling pathway." (PMID 36147923, 2022). "Altogether, these results showed that INPP4B overexpression restrains T cell-suppression by glioma cells." (PMID 36147923, 2022).
glioma (continued). "We found that INPP4B overexpression restrained the proliferation, migration, apoptosis resistance, PD-L1 expression, and T cell suppression by glioma cells, whereas INPP4B silencing had the opposite effects." (PMID 36147923, 2022). "In summary, here we present evidence that INPP4B expression is downregulated in glioma tissues and cells, and that INPP4B overexpression inhibits cell growth, migration, and apoptosis resistance of glioma cells." (PMID 36147923, 2022). "For this reason, we endeavored to establish a mouse orthotopic brain glioma model, which showed that INPP4B expression was lower in glioma tissues than in normal brain tissues." (PMID 36147923, 2022). "INPP4B overexpression obviously inhibited glioma cell proliferation and migration, while inducing G0/G1 cell cycle arrest." (PMID 36147923, 2022). "Meanwhile, our study found that INPP4B expression was negatively correlated with PD-L1 expression in glioma cells." (PMID 36147923, 2022). "The abnormal expression from INPP4B we identified in clinical samples from glioma patients constitutes a valuable insight for future studies." (PMID 36147923, 2022). "We found that INPP4B overexpression restricted the proliferation, migration, apoptotic resistance, and PD-L1 expression by glioma cells, thereby inhibiting immune escape." (PMID 36147923, 2022). "We provided evidence that INPP4B is expressed at low levels in glioma tissues and is negatively correlated with the pathological grade of glioma." (PMID 36147923, 2022). "The effects of INPP4B on glioma cell growth and migration was tested in vitro by CCK-8, cell cycle and transwell assays." (PMID 36147923, 2022). "INPP4B (Inositol polyphosphate 4-phosphatase type II) has been regarded as a suppressor of several human tumors, but its biological function, expression, and clinical significance in glioma tissues and cell lines are unclear." (PMID 36147923, 2022). "In short, INPP4B overexpression restrains glioma cell proliferation, migration, and PD-L1 expression by down-regulating PI3K/AKT signaling." (PMID 36147923, 2022). "Thus, INPP4B knockdown promotes glioma cell proliferation, migration, and PD-L1 expression by up-regulating PI3K/AKT signaling." (PMID 36147923, 2022). "Collectively, these data support that INPP4B may inhibit glioma progression, and particularly, glioma’s immune escape." (PMID 36147923, 2022). "In addition, we verified that INPP4B was expressed at higher levels in low- than in high-grade glioma samples." (PMID 36147923, 2022). "Collectively, these findings demonstrated that in vitro, INPP4B suppresses glioma cell progression." (PMID 36147923, 2022). "Moreover, we showed that INPP4B inhibited glioma cell proliferation, migration, and PD-L1 expression by downregulating PI3K/AKT signaling." (PMID 36147923, 2022). "Through overexpression and knockdown of INPP4B in U87 and U251 glioma cells we showed that INPP4B could inhibit the proliferation, migration, and apoptosis resistance of glioma cells." (PMID 36147923, 2022). "In addition, INPP4B overexpression in glioma cells could overcome the suppression they exerted on the proliferation of co-cultured T cells." (PMID 36147923, 2022). "Therefore, whether the abnormal expression of INPP4B contributes to the deterioration of astrocytes into glioma deserves further exploration." (PMID 36147923, 2022). "In addition, INPP4B may inhibit the proliferation, migration, apoptosis resistance and immune escape of glioma by negatively regulating PI3K/AKT signaling." (PMID 36147923, 2022). "Thus, INPP4B might be an attractive target for therapeutic intervention against glioma." (PMID 36147923, 2022). "Thus, INPP4B may constitute a valuable target for glioma treatment." (PMID 36147923, 2022). "Notably, whether INPP4B participates in immune escape of glioma deserves urgent attention." (PMID 36147923, 2022).
glioma (continued). "Since the function of INPP4B in glioma has not been reported, we sought to probe its suppressive or pro-tumoral effect on this malignancy." (PMID 36147923, 2022). "We could infer that inhibiting the expression of INPP4B could activate the PI3K/AKT pathway, and thus upregulate PD-L1 expression, and ultimately, inhibit glioma’s immune escape." (PMID 36147923, 2022). "INPP4B and its control on PI3K/AKT pathway may play a critical role in the development of glioma." (PMID 36147923, 2022).
metabolic syndrome (3 papers, 2021 to 2025). A cluster of metabolic risk factors for CARDIOVASCULAR DISEASES and TYPE 2 DIABETES MELLITUS. "INPP4B protects against metabolic syndrome and associated disorders and EXOC4 is involved in insulin-stimulated glucose transport and is associated with type II diabetes and fasting glucose." (PMID 38483771, 2024). "Adipose expansion and inflammation are downregulated by INPP4B in obese animals, suggesting a protective role for INPP4B from metabolic syndrome." (PMID 33772116, 2021). "Thus, Inpp4b−/− males faithfully reproduce the complex metabolic syndrome in men and, accordingly, the INPP4B signaling cascade should be considered for therapeutic intervention in this wide-spread disease." (PMID 33772116, 2021). "Abnormal Hoxc4 expression in fat is sufficient to modulate metabolic function in mice and humans, while Inpp4b-KO males (but not females) have marked metabolic syndrome with higher adipose levels, insulin resistance, and inflammation in the adipose tissue." (PMID 40161793, 2025).
metastatic disease (3 papers, 2014 to 2023). "Taken together, these findings point to a critical role of INPP4B in overall patient survival and metastatic disease." (PMID 25868852, 2015). "In advanced metastatic tumors, transcript levels of INPP4B and EZH2 do not correlate." (PMID 38001678, 2023).
osteoporosis (3 papers, 2017 to 2025). A condition of reduced bone mass, with decreased cortical thickness and a decrease in the number and size of the trabeculae of cancellous bone (but normal chemical composition), resulting in increased fracture incidence. "In humans, we showed that specific INPP4B variants were associated with variable bone mineral density and established INPP4B as a susceptibility locus to osteoporosis in pre-menopausal women." (PMID 32764302, 2020). "Consequently, mice lacking INPP4B suffer from bone loss and osteoporosis, as INPP4Bα acts on intracellular calcium to inhibit the nuclear localization of NFATc1 and subsequently the transcription of osteoclast-specific target genes." (PMID 40573111, 2025).
Achalasia (2 papers, 2022 to 2024). A disorder of esophageal motility characterized by the inability of the lower esophageal sphincter to relax during swallowing and by inadequate or lacking peristalsis in the lower half of the body of the esophagus. "INPP4B overexpression is associated with human achalasia, which is a rare motility disorder characterized by myenteric neuron and interstitial cells of Cajal abnormalities." (PMID 35440622, 2022). "The c-kit downregulation and INPP4B upregulation, validated by western blot and immunohistochemistry, extend previous data showing a loss of the ICC network in tissues from patients with achalasia and indicate a general increase in inhibitory signals for cell survival." (PMID 39337632, 2024).
acute lymphoblastic leukemia (2 papers, 2011 to 2018). Leukemia with an acute onset, characterized by the presence of lymphoblasts in the bone marrow and the peripheral blood. "The overexpression of INPP4B first became evident after the analysis of gene expression in leukemic blasts from BCR/ABL-positive pediatric acute lymphoblastic leukemia." (PMID 29343273, 2018). "The first evidence of INPP4B involvement in tumorigenesis came from analysis of gene expression in the leukemic blasts from 132 patients to select for highly ranked class discriminators in pediatric acute lymphoblastic leukemia (ALL)." (PMID 21487159, 2011).
bladder tumor (2 papers, 2014 to 2015). "Immunohistochemistry showed that INPP4B was positive in 62% of bladder tumors, which was significantly lower than in benign urothelial tissues (87%; P < 0.001)." (PMID 26770009, 2015). "We investigated the expression of INPP4B in 129 bladder tumor specimens as well as 87 benign bladder tissues by immunohistochemistry staining." (PMID 25277204, 2014). "However, no prognostic significance of INPP4B expression in bladder tumors has been demonstrated." (PMID 26770009, 2015).
cardiac arrest (2 papers, 2023). Cessation of breathing and/or cardiac function. "It was confirmed that during cardiac arrest/cardiopulmonary resuscitation (CA/CPR), the binding of miR-137 by GAS5 increases the expression of inositol polyphosphate-4-phosphatase type II B (INPP4B)." (PMID 36672665, 2023). "A recent study showed that exosomes isolated from plasma samples of cardiac arrest/cardiopulmonary resuscitation (CA/CPR) patients contained abundant levels of GAS5, which targets inositol polyphosphate-4-phosphatase type II B (INPP4B) through the sponge effect with miR-137." (PMID 38132140, 2023).
gallbladder cancer (2 papers, 2021 to 2023). "By contrast, INPP4B downregulation reduced proliferation and increased apoptosis of gastric, pancreatic, and gallbladder cancer cells, while INPP4B overexpression leads to opposing effects." (PMID 36993823, 2023). "INPP4B levels are significantly reduced in human hepatocellular, gastric, and gallbladder carcinoma." (PMID 36993823, 2023). "The INPP4B protein expression levels in gallbladder cancer tissues and normal gallbladder tissues were detected by immunohistochemistry, and the clinical significance of INPP4B was analysed." (PMID 33879096, 2021). "However, the its biological role played by INPP4B in human gallbladder cancer (GBC) has not been elucidated." (PMID 33879096, 2021).
Hyperglycemia (2 papers, 2020 to 2021). An increased concentration of glucose in the blood. "Inpp4b-deficient animals developed hyperglycemia on normal chow and T2D on HFD due to decreased insulin sensitivity." (PMID 33772116, 2021). "However, the similarity between the dose responses for PI3P and PIP3 suggested their interconversion may be a direct influence of hyperglycemia on the depression of INPP4B activity and increased expression of Sac3 as previously discussed." (PMID 32230859, 2020). "Hence, these results suggested that hyperglycemia alone cannot trigger the PI3K, PTEN, and INPP4B impacts seen in the metformin study, while potentially muting the TNBC PI3K and Sac3 activity." (PMID 32230859, 2020).
lung adenocarcinoma (2 papers, 2020 to 2024). A carcinoma that arises from the lung and is characterized by the presence of malignant glandular epithelial cells. "In order to elucidate the molecular mechanism of INPP4B in regulating genome integrity in lung cells, we generated INPP4B knockout cell lines by Crispr-Cas9 gene editing technology targeting the exon of INPP4B gene in lung adenocarcinoma cell line A549." (PMID 32341333, 2020). "Here we report knockout of INPP4B in lung adenocarcinoma A549 cells by Crispr-Cas9 gene editing leads to sensitization to ionizing radiation (IR), PARP inhibitor olaparib and impaired DNA homologous recombination repair." (PMID 32341333, 2020).
metastatic cancers (2 papers, 2023). A carcinoma which has spread from the original site of growth to another anatomic site. "Both INPP4B and PTEN display modest rates of copy number alterations (CNAs) in primary tumors and a significant loss of expression in metastatic cancers, with the corresponding increase in PI3K/Akt signaling in all metastases." (PMID 38001678, 2023). "One of the upregulated genes potentially driving the oncogenic role of INPP4B in RB is the macrophage-capping protein (CAPG) which raised the expression of CAPG was likewise shown in different metastatic cancers, supporting its involvement in tumor cell invasion and metastatic processes." (PMID 36993823, 2023). "The phosphatases INPP4B and PTEN are tumor suppressors that are lost in nearly half of advanced metastatic cancers." (PMID 38001678, 2023).
multiple myeloma (2 papers, 2021 to 2023). "In a most recent study, decreased INPP4B expression levels were reported for multiple myeloma cell lines as well as bone marrow plasma of multiple myeloma patients, and lower INPP4B levels correlated with a poor outcome." (PMID 36993823, 2023). "We further demonstrate that INPP4B inhibits the proliferation and chemosensitivity of myeloma cells via disturbing PI3K/Akt/mTOR signaling and exerts a tumor suppressor effect." (PMID 35070988, 2021). "Inositol polyphosphate-4-phosphatase type II (INPP4B) has been identified as a tumor suppressor, while little is known about its expression and function in multiple myeloma (MM)." (PMID 35070988, 2021). "To further explore the potential mechanism of INPP4B inhibiting myeloma cells proliferation, we detected the effect of INPP4B on PI3K/Akt signaling pathways according to the previous reports." (PMID 35070988, 2021).
pancreatic ductal adenocarcinoma (2 papers, 2018 to 2025). An infiltrating adenocarcinoma that arises from the epithelial cells of the pancreas. "Increased expression of inositol polyphosphate 4-phosphatase, type II (INPP4B) correlates with aggressive phenotypes in pancreatic ductal adenocarcinoma (PDAC)." (PMID 40962057, 2025). "To date, little is unveiled about whether and how INPP4B will exert its tumor suppressive function on the turnover of cadherin-based cell-cell adhesion system in pancreatic ductal adenocarcinomas (PDACs) in vitro." (PMID 29952716, 2018).
schizophrenia (2 papers, 2010 to 2025). A major psychotic disorder characterized by abnormalities in the perception or expression of reality. "The schizophrenia susceptibility genes detected in inh-PVALB neurons in the midbrain included genes such as DGKZ, INPP4B and TKT." (PMID 39397771, 2025).